CD14 (CD14 molecule)
Diseases named in the same sentence as CD14 in open-access papers (continued):
Sharing a sentence is not in itself a finding about the gene and the disease.
COVID-19 (continued). "Compared to both healthy controls and patients with viral or bacterial pneumonia, COVID-19 patients, especially severe cases, have in their peripheral blood reduced numbers of CD14+CD16-DR+ “classical” monocytes, which may be due to the increased levels of IL-6 and/or dysregulated myelopoiesis." (PMID 33481950, 2021). "In module 2, mono-CD14+ cells in patients with severe COVID-19 exhibited higher expression levels of glycolysis-related genes (LDHA and PKM) and PPP-related genes (PGD and TKT), which may be involved in the proinflammatory response (upregulation of S100A8, S100A9, S100A12, and IL1B)." (PMID 33936072, 2021). "Further studies are necessary to define whether these cells are immature precursors of the granulocytic/monocytic lineage or a new subset of circulating monocytes, as well as the extent of their overlap with the immature CD14+ cells described in COVID-19 patients and sepsis." (PMID 33674591, 2021). "Notably, in severe/critical COVID-19 patients in the recovery stage, the proportion of CD14 monocytes (based on the expression of the marker genes CST3, LYZ, CD14) in PBMCs were elevated, but CD4 T cells (IL7R, LTB) were decreased, consistent with a previous report." (PMID 35046942, 2021). "Moreover, we found enhanced glycolysis and PPP activity in mono-CD14+ cells of patients with severe COVID-19, which may be responsible for these inflammatory responses." (PMID 33936072, 2021). "Furthermore, the percentages of CD14+TREM-1+ were lower in those COVID-19 patients." (PMID 34960790, 2021). "Thus, in COVID-19 patients, GM-CSF potentially links the severe-pulmonary-syndrome-initiating capacity of pathogenic Th1 cells (GM-CSF+IFN-γ+) with the inflammatory signature of monocytes (CD14+CD16+ with high expression of IL-6) and their progeny." (PMID 34676125, 2020). "In severe COVID-19, elevated OPN plasma levels activated CD14 monocytes and PD-L1+ neutrophils, contributing to disease progression." (PMID 40704794, 2025). "By using published datasets of spatial transcriptomics and single-cell RNAseq, we show that ADA2 is highly expressed by inflammatory CD14+CD16+ monocytes, along with profibrotic genes, in lungs affected by COVID-19." (PMID 40332245, 2025). "Here, the proportion of CD14+ monocyte cells and the expression level of CXCR3 of Tregs in severe COVID-19 patients supported that the ligand-receptor pair of PF4_CXCR3 promotes the activation of HLA_DR+ Tregs in severe COVID-19 patients." (PMID 40114921, 2025). "CD14 + CD16 − monocytes are a classical monocyte subset, which was reported to be decreased in severe COVID-19 cases." (PMID 38844850, 2024). "In our investigation, we have identified significant transcriptomic alterations, particularly in the genes CD3, CD14, CD16, FOSB, S100A12, and TCRɣδ, that differentiate sepsis, mild COVID-19, septic shock, and severe COVID-19." (PMID 38892107, 2024). "For example, individuals with moderate COVID-19 demonstrated lower levels of FOSL2, MAX, MAFB, IRF1, RUNX3, and HIF1A in CD14 and CD16 monocytes from other cohorts." (PMID 39712003, 2024). "We then analyzed the HERV loci transcriptomes from studies that have shown activated CD14 + monocytes: PBMC activated in vitro by LPS and PBMC from separate datasets of patients with physical trauma or from patients hospitalized with COVID-19." (PMID 39497142, 2024). "Transcriptomic analyses of PBMCs from patients with acute COVID-19 showed that upregulated genes were enriched in bone marrow, blood CD33+ myeloid cells, and CD14+ monocytes." (PMID 39205185, 2024). "Out of a pool of more than 60 parameters, we identified NK-cell precursors, CD14+CD91+ monocytes, and CD8+ Effector Memory T cells as those variables with the highest impact on COVID-19 severity and patient survival." (PMID 39136010, 2024). "Both CD9 and CD63 are involved in exosome formation, and COVID-19 plasma exosomes stimulate pro-inflammatory responses that affect CD4/CD8 T cells, and CD14+ monocytes." (PMID 39712003, 2024).
COVID-19 (continued). "The increase in monocytes, specifically those exhibiting an activated M1 effector phenotype (CD14/CD16/HLA-DR), played a key role in mucosal protection, antiviral mechanisms, and the antigen presentation process in response to COVID-19." (PMID 38675784, 2024). "In this study, we first found that the gene expression of NLRP3 and IL-1β was downregulated in the CD14+ and CD16+ monocytes from COVID-19 patients, while MARCH7 and IL-18 declined only in the CD16+ monocytes." (PMID 38004809, 2023). "For the three selected cell types, differential analysis between COVID-19 and control groups returned 3,061 sites for CD8 TEM, 1,301 sites for CD14 Mono, and 1,778 sites for NK (Methods section ‘COVID-19 PBMC scATACseq data analysis’)." (PMID 37974651, 2023). "The analysis focused on the CD41+, CD14+, and CD142+ EVs, which were statistically different between the COVID-19 coagulopathy and the healthy volunteer groups." (PMID 37240566, 2023). "Inflammatory cytokines are released by classic (CD14+CD16+) and intermediate (CD14+CD16+) monocytes in severe COVID-19 cases." (PMID 36839601, 2023). "We observed that both PBMCs and monocytes had upregulated expression of mRNAs of myeloid markers, including CD14, α-integrins (CD11b and CD11c), FCγ receptors (CD64A), and macrophage scavenger receptors (CD163), as a function of the severity of COVID-19." (PMID 37310504, 2023). "The cell proportion makeup differed drastically between PPASC and severe COVID-19, with CD16+ monocytes and dendritic cells found to be significantly increased and CD14+ monocytes significantly decreased in PPASC compared to severe COVID-19." (PMID 38259488, 2023). "TNF-α positively correlated with inflammatory CD14+CD16+ and patrolling CD16+ monocytes in pregnant women with acute COVID-19, while negatively correlating with classical CD14+ monocytes and activated NK cells." (PMID 37036008, 2023). "VEGFA and its ligand expression was minimal in CD14+ and CD16+ monocytes in the severe COVID-19 but was over 40% in dendritic cells." (PMID 38259488, 2023). "When we further analyzed ACE2 and CD16 surface expression in the CD14+ monocytes by our gating strategy, we indeed found co-expression of ACE2 and CD16 in CD14+ monocytes at a variety of levels from healthy control and COVID-19 patients." (PMID 36085197, 2022). "Our findings suggested that select subpopulations of T cells, including Th-17 cells, Treg cells, and CD4+ central memory T cells, were less responsive to COVID-19 plasma exosomes than CD4+ T cells, CD8+ T cells, and CD14+ monocytes." (PMID 36526691, 2022). "An overall reduced abundance of monocytes in severe with increased CD14+ and decreased CD16+, CD16+CD14+ monocytes in severe COVID-19." (PMID 36072602, 2022). "We found higher frequencies of neutrophils, intermediate CD14+CD16+monocytes, activated HLA-DR+CD38+ CD4+ T cells, EM-like CD4+ and CD8+ T cells in COVID-19 respiratory compared to blood samples." (PMID 35589689, 2022). "The CD14+CD16- cMo, CD14+CD16+ iMo and CD14-/loCD16+ ncMo were examined to compare COVID-19 patients to healthy controls." (PMID 36685582, 2022). "Hospitalized COVID-19 patients with more severe disease had a relatively higher frequency of cMono and fewer intermediate monocytes (CD16+CD14+), ncMono (CD14−CD16+), and DCs." (PMID 35216673, 2022). "Comparative analyses between rheumatoid arthritis and COVID-19 samples revealed similar pro-inflammatory disease patterns regulated via SPP1 and S100A12, leading to activation of proinflammatory CD14+ monocytes and PD-L1+ neutrophils." (PMID 35681519, 2022). "Three studies demonstrated a high proportion of CD14+ and CD16+ cells in patients with severe COVID-19, with inflammatory factors including GM-CSF and IL-6, IL-10 and TNF-α." (PMID 35843719, 2022). "Our study found that levels of plasma gp96 and IL-6 were closely correlated in COVID-19 patients that and gp96 can act as DAMP to activate CD14+ cells to secrete IL-6." (PMID 34817280, 2021).
COVID-19 (continued). "In addition, inflammatory monocytes, characterized by the expression of S100A8, S100A9, VCAN, FCN1, CD14, and CD62L, also display an IFN signature, which has been associated with a profibrosis differentiation pattern and were more abundant in severe than in mild COVID-19." (PMID 34209845, 2021). "Compared to patients with mild COVID-19, severely ill patients showed downregulation of IFN response in mono-CD14+ cells but upregulation of IFN response in mono-CD14+CD16+ cells." (PMID 33936072, 2021). "One study showed increased classical CD14+HLA-DRhi monocytes with high IFI6 and ISG15 expression in mild COVID-19 cases when compared to healthy controls, similar to our findings." (PMID 34108966, 2021). "We observed a significantly increased frequency of CD163+ CD14+ cells and decreased frequency of CD163+ CD14– cells in the DC3 subset in COVID-19 patients compared to controls." (PMID 34614036, 2021). "While cell numbers were higher in blood, higher frequencies of intermediate (CD14+CD16+) monocytes/macrophages, activated (HLADR+CD38+) and EM-like (CD27−CD45RA−) CD4+ and CD8+ T-cells were found in COVID-19 respiratory specimens compared to blood." (PMID 34462740, 2021). "Fifth, there was no statistical difference in the total CD11b+CD14+ monocytes between convalescent COVID-19 and HD, but a specific CXCR3+ CD11b+CD14+ monocyte subset was significantly increased during disease convalescence." (PMID 34113347, 2021). "When PBMCs from healthy donors were treated in vitro with cortisol at the averaged maximal levels in severe/critical COVID-19, the numbers of CD8+, CD56+, and CD14+ cells were significantly reduced." (PMID 34103487, 2021). "We found the expansion of myeloid DCs, CD14+ monocytes, and MP/platelets in most of the patients with COVID-19, and decreased CD16+ monocytes and NKs in more than half of the patients with COVID-19." (PMID 33677468, 2021). "In the pooled COVID-19 patients, ACE2 was expressed in several immune cells, such as dendritic cells, CD14 monocytes, CD4 memory T cells, CD4 naive T cells, CD8 effector T cells, etc.; TMPRSS2 was expressed in most immune cells." (PMID 34578338, 2021). "Concurrently, current research in COVID-19 has highlighted the overactivation of CD14+ monocytes and the emergence of novel monocytic subsets including myeloid-derived suppressor cell (MDSC)-like suppressive monocytes within COVID-19 patients." (PMID 34721400, 2021). "Although we did not examine HLA-DR protein expression in this study, HLA-DR cell surface protein expression was reported to be decreased in CD14+ and CD16+ monocytes in people with COVID-19, with decreased expression correlating with disease severity." (PMID 34108966, 2021). "We observed that the reduction in the expression of TREM-1 on the cell surface in CD14+ and CD16+ leukocytes from the blood of COVID-19 patients was accompanied by a concomitant increase in plasma levels of sTREM-1." (PMID 34960790, 2021). "First, we found that monocytes (CD14 and CD68) infiltrated the lungs and intestines of patients with COVID-19." (PMID 33424804, 2020). "Consequently, high levels of Th1, Th17, and inflammatory CD14+CD16+ monocytes release more cytokines that activate macrophages and fibroblasts resulting in overwhelming amounts of proinflammatory cytokines associated with severe lung pathology in COVID-19 patients." (PMID 33623561, 2020). "did not observe substantial expression of proinflammatory cytokine genes on circulating monocytes in COVID-19, they did identify severe cases of COVID-19 showing a depletion of CD16+ monocytes and a prominent shift toward CD14+ monocytes." (PMID 33584679, 2020). "We further identified strong genetic correlations (|r| > 0.5) between smaller sets of proteins related to COVID-19 severity, and host proteins relevant to viral replication such as between IL-6-induced proteins (SAA1, SAA2, and CD14) and fibulin 5 (FBLN5)." (PMID 33328453, 2020).
COVID-19 (continued). "This corroborates with our data where, contrary to CCL2, serum CX3CL1 was quicky augmented suggesting that non-classical monocytes (NC; CD14+/-CD16++/CX3CR1+) rather than classic monocytes (CL; CD14++CD16−/CCR2+) are the first actors during COVID-19." (PMID 40710346, 2025). "However, we observed an enhanced interaction between PF4 from CD14+ monocytes and CXCR3 from HLA_DR+ Tregs in COVID-19 patients, suggesting that PF4-CXCR3 plays an important role in maintaining homeostasis and suppressive function of Tregs." (PMID 40114921, 2025). "In addition, only mild/moderate COVID-19 samples were enriched for CD16 monocytes, and severe Delta cases were accompanied by the depletion of classical Mon CD14." (PMID 39712003, 2024). "A decision tree including the main clinical, laboratory, and biological variables at admission identified low NK-cell precursors and CD14+CD91+ monocytes, and high CD8+ Effector Memory T cell frequencies as the most robust immunological correlates of COVID-19 severity and reduced survival." (PMID 39136010, 2024). "Unlike adult patients, children with COVID-19 showed lower frequencies of activated proinflammatory CD14+ monocytes, possibly explaining the rareness of cytokine storm in them." (PMID 39148728, 2024). "Monocytes (HLADR+CD14+/low CD16−/+) showed little to no CASP1+ signal in both COVID-19 and healthy donors." (PMID 39240187, 2024). "Thus, we analyzed CD15+CD66b+CD14– neutrophils in the PBMC fractions from healthy controls and from patients with mild and severe COVID-19." (PMID 39253969, 2024). "In addition, there were 266 DEGs in CD14 Mono, and we further clustered CD4 Mono into four subpopulations and tried to identify MS1 related subpopulations, which have been reported to be associated with severe COVID-19 and sepsis, and their changes at six months after infection are unknown." (PMID 38503738, 2024). "Similarly, for CD14 and CD16 monocyte cells in severe COVID-19, CEBPD and FOS were particularly activated in the two cell types, and CEBPD upregulated S100A8 and S100A9." (PMID 37936693, 2023). "The current study showed that patients under CHD hospitalized for moderate COVID-19 have increased circulating levels of TNFα, IFNγ and PDGF-A, decreased CD14-lymphocytes, decreased CD19-lymphocytes and decreased expression of HLA-DR on CD14-monocytes." (PMID 37674148, 2023). "In addition to the S100A12-TLR4-inflammatory response, COVID-19 acute necrotizing encephalopathy patients were accompanied with an IFN-1 response, dominant in classical monocytes (Mono_CD14)." (PMID 37848421, 2023). "Fibrocytes are known to migrate via CXCR4-CXCL12-mediated activity during fibrotic remodeling, and we found that this receptor was significantly upregulated in CD14+ monocyte populations in PPASC but not in severe COVID-19." (PMID 38259488, 2023). "Immune response pathways were found to be downregulated in CD14+ monocytes but not in CD16+ monocytes or dendritic cells in PPASC compared to severe COVID-19." (PMID 38259488, 2023). "The numbers of CD41+ EVs, CD14+ EVs, and CD142+ EVs were statistically higher in the COVID-19 coagulopathy group, thereby supporting our hypothesis of an association between COVID-19 coagulopathy and EVs." (PMID 37240566, 2023). "Moreover, we observed an increase in CD14+ monocytes and a decrease in CD16+ monocytes in patients with COVID-19-induced ARDS." (PMID 37363730, 2023). "scRNA-seq analysis of PBMCs from two control and two COVID-19 patients (WHO-graded cohort) charted all expected myeloid and lymphoid populations and discriminated four monocyte populations along the CD14-, CD16-, and HLA-expression scheme." (PMID 35998224, 2022). "A pharmacological inhibitor of TLR3 considerably reduced cytokine and chemokine production by CD4+ and CD8+ T cells but not by CD14+ monocytes, highlighting divergent signaling pathways of immune cells in response to COVID-19 plasma exosomes." (PMID 36526691, 2022).
COVID-19 (continued). "Similarly, it has been previously reported that upregulation of C-Mo and, in particular, higher numbers of CD14+ CD33+ HLA-DR cells and S100A8/9/12 expressing C-Mo are present in severe/critical COVID-19 and sepsis." (PMID 36969980, 2022). "We found that the number of CD14+ classical monocytes was increased in the patient with myopericarditis after COVID-19 vaccination, while CD16+ non-classical monocytes were increased in the recently vaccinated controls." (PMID 35251049, 2022). "Representative dot-plots illustrate the comparison of CD14+CD16+ non-classical monocytes expressing IFN-alpha in blood samples treated with polyclonal stimuli from participants who developed mild or severe COVID-19 during the follow-up." (PMID 35860236, 2022). "Targeting TNFSF10 and IFITM2 in CD14+ and CD16+ monocytes may affect the immune response of COVID-19 patients with cancer." (PMID 36555339, 2022). "Expansion of CD14+CD16+ monocytes that express high level of IL-6 was significantly higher in COVID-19 patients admitted to ICU compared to those who did not." (PMID 36369012, 2022). "In contrast, intracellular TGF-β expression in non-M-MDSCs (HLA-DR-/low CD11b+CD14-TGF-β+ cells) significantly higher in severe COVID-19 patients compared with both moderate COVID-19 and HC groups (all P < 0.0001)." (PMID 36581679, 2022). "PD-L1 was enhanced in c-FLIP-expressing CD14+ cells, in agreement with our previous findings in pancreatic ductal adenocarcinoma (PDAC) patients, hinting to common mechanisms of innate immunity modulation in COVID-19 and cancer." (PMID 34518653, 2022). "Similarly, COVID-19 plasma exosomes from patients in both their early and late hospitalization stimulated the expression of IL-6, IL-8, and TNF-α in CD14+ monocytes." (PMID 36526691, 2022). "Similarly, a greater abundance of inflammatory monocytes (CD14++IL-1b+) enriched with inflammatory genes (e.g. CCL4, CXCR4, and ISGs) was found in COVID-19 patients." (PMID 35284964, 2022). "Mono-CD14-IFITM3 and Mono-CD14-CD16 are two monocyte subtypes responsible for initiating the interferon signaling pathway in response to infection and are specific to COVID-19 patients." (PMID 36289881, 2022). "It has also been noted that a higher level of CD14+ and/or CD16+, due to periodontitis, could enhance COVID-19 aggravation." (PMID 35224542, 2022). "The classical monocyte population also followed a pattern like the NK cells, while the CD14+/CD16+ Intermediate monocyte, highly abundant in the healthy individuals, decreased significantly in the COVID-19 patients followed by an increase in the recovered individuals." (PMID 36532041, 2022). "Granulocytes and monocytes/macrophages dominate in COVID-19 airways, especially intermediate (CD14+CD16+) and non-classical (CD14-CD16+) monocytes." (PMID 35589689, 2022). "In their study, blood CD14+CD16‒ classical monocytes from COVID-19 patients did not express surface ACE2 upon LPS stimulation and failed to be infected by SARS-CoV-2." (PMID 36085197, 2022). "In the other hand, CD14, LBP and LRG1 might indicate the progression of lung damage in COVID-19 patients." (PMID 35884998, 2022). "Additional immunological features associated with severe COVID-19 with lower weight values included lower CD16 expression by neutrophils, lower percentages of non-classical (CD14−CD16+) and intermediate (CD14+CD16+) monocytes and lower numbers of NK cells." (PMID 35386227, 2022). "No clear correlation was observed in any of the two contrasts, which suggests that the transcriptional signature of CD14+ monocytes in moderate COVID-19 is not similar to that of monocytes in sepsis." (PMID 36572683, 2022). "A significant expansion of populations of CD14+CD16+ monocytes producing IL-6 was observed in the peripheral blood of patients with COVID-19 in ICU compared with those patients who did not require ICU hospitalization." (PMID 34658642, 2021).